PPARGC1A (PPARG coactivator 1 alpha)
Diseases named in the same sentence as PPARGC1A in open-access papers (continued):
Sharing a sentence is not in itself a finding about the gene and the disease.
hepatocellular carcinoma (56 papers, 2008 to 2025). A malignant tumor that arises from hepatocytes. "Research indicates that the protein PPARGC1A is linked to the development of hepatocellular carcinoma (HCC), although its exact functions and related pathways are not fully understood." (PMID 39108264, 2024). "The involvement of EHD4 and PPARGC1A in hepatocellular carcinoma may be mediated by the regulation of tumor-associated macrophages (TAMs) and other immune cells." (PMID 40564032, 2025). "Previous studies are mainly focused on the association between PPARGC1A and hepatoma." (PMID 29361788, 2018). "Although this study combined multi-omics data, Mendelian randomization, and animal model systems to reveal the potential role of EHD4 and PPARGC1A in hepatocellular carcinoma, certain limitations remain." (PMID 40564032, 2025). "Notably, PPARGC1A was up-regulated in our DEN-induced rat HCC model, whereas several large-scale human studies have documented a marked down-regulation of PPARGC1A in hepatocellular carcinoma and linked its low expression to poor prognosis." (PMID 40564032, 2025). "In summary, genome-wide association studies (GWASs) in recent years still provide relatively limited genetic evidence for EHD4 and PPARGC1A in hepatocellular carcinoma." (PMID 40564032, 2025). "In the previous studies, we compared the PPARγ, PPARGC1A, and PPARGC1B SNVs with susceptibility of esophageal, colorectal, and hepatocellular carcinomas." (PMID 36587194, 2022). "In conclusion, these results suggested that miR-93-5p overexpression contributes to hepatoma development by inhibiting PPARGC1A." (PMID 29361788, 2018). "All hepatoma cell lines showed lower expression of PPARGC1A than L-02 cells, while there was an increase in the expression of miR-93-5p in hepatoma cell lines compared with L-02 cells, especially in Huh7 cells." (PMID 29361788, 2018). "In general, experimental results above suggested that miR-93-5p is up-regulated whereas PPARGC1A is down-regulated in the hepatoma development." (PMID 29361788, 2018). "In this study, we aim to clarify the role of miR-93-5p and its regulation mechanism on PPARGC1A in the hepatoma cells proliferation." (PMID 29361788, 2018). "Next, we analyzed the expression levels of PPARGC1A and miR-93-5p in six hepatoma cell lines and human hepatic cell L-02 using quantitative Real-Time PCR (qRT-PCR) and western blot." (PMID 29361788, 2018). "Down-regulated genes include RAMP2 and PPARGC1A, and their inactivation or under-expression was shown to contribute to lung cancer and hepatoma development respectively." (PMID 20015407, 2009). "In hepatocellular carcinoma, the hypoxia-responsive PPARGC1A (peroxisome proliferator activated receptor gamma coactivator 1 alpha)/BAMBI (bone morphogenetic protein and activin membrane bound inhibitor)/ACSL5 (acyl-CoA synthetase long chain family member 5) pathway confers lenvatinib resistance." (PMID 39935430, 2025). "PPARGC1A is involved in the progression and prognosis of different types of cancer, such as clear cell renal cell carcinoma, pancreatic cancer, breast cancer and, lately, also in hepatocellular carcinoma (HCC)." (PMID 37681914, 2023). "Therefore, having verified that hsa-miR-193b-3p overexpression in HepG2 hepatoma cells reduced the expression of PPARGC1A, we proceeded to analyze the intracellular lipid content in these cells." (PMID 36835287, 2023). "It was found that miR‐30b‐5p might regulate lipid metabolism by targeting the Ppargc1a in hepatocellular carcinoma Huh‐7 cells." (PMID 33282259, 2020). "Taken together, we propose that the miR-93-5p–PPARGC1A pair regulates hepatoma progression." (PMID 29361788, 2018). "Furthermore, mechanism analysis suggested that miR-93-5 directly targeted PPARGC1A mRNA to result in hepatoma cell proliferation." (PMID 29361788, 2018).
hepatocellular carcinoma (continued). "Eventually, our study identified EHD4 and PPARGC1A as key regulators in hepatocellular carcinoma (HCC), particularly through their roles in modulating tumor-associated macrophages (TAMs) and other immune cells within the tumor microenvironment." (PMID 40564032, 2025). "A recent study on hepatocellular carcinoma (HCC) found that ferroptosis is regulated by the PPARGC1A/BAMBI/ACSL5 axis, with METTL3 and WTAP inhibiting PPARGC1A in an m6A- and YTHDF2-dependent manner." (PMID 40271153, 2025). "Additionally, in hepatocellular carcinoma, PPARGC1A was positively correlated with resting mast cells and negatively correlated with activated mast cells, suggesting that PPARGC1A may play a key role in regulating the mast cell activation status in the tumor microenvironment." (PMID 40564032, 2025). "Collectively, these results revealed that miR-93-5p inhibited PPARGC1A and CDKN1A genes, thereby decreasing the expressions of transcription factors CEBPB and promoting hepatoma cells proliferation." (PMID 29361788, 2018). "In hepatocellular carcinoma (HCC), miR-93-5p was found to be upregulated and promote cell proliferation by downregulating peroxisome proliferator-activated receptor gamma coactivator-1 alpha (PPARGC1A)." (PMID 39677943, 2024). "Furthermore, we found significant differences in clinicopathological characteristics (age, gender, fibrosis Ishak score, pathologic T, and race) between HSPA1A, NR1I3, PPARGC1A, and MAT1A gene expressions and hepatocellular carcinoma patients." (PMID 37993485, 2023). "For hsa_circ_0004315, some studies have found that this circRNA may act as a molecular sponge for miRNAs such as hsa-miR-214-3p and hsa-miR-195-5p to regulate the expression, respectively, of PPARGC1A and CCNE1 in hepatocellular carcinoma and breast cancer." (PMID 35322101, 2022). "Wang et al59 found that, in patients with hepatocellular carcinoma, miR‐93‐5p can directly target 3'‐UTR in the mRNA of PPARGC1A (also known as PGC‐1a), inhibiting the expression of PPARGC1A, which functions as a coactivator of transcription and a metabolic modulator." (PMID 31411003, 2019). "MRPL54, EZH2, PPARGC1A, and EIF2AK4 were identified as hub genes in bioinformatics analysis of hepatocellular carcinoma (HCC)." (PMID 35719986, 2022).
Alzheimer disease (55 papers, 2009 to 2026). A progressive, neurodegenerative disease characterized by loss of function and death of nerve cells in several areas of the brain leading to loss of cognitive function such as memory and language. "On the other hand, PPARGC1a overexpression can exacerbate Aβ and hyperphosphorylated tau deposition in mice model of Alzheimer’s disease." (PMID 31139208, 2019). "PPARGC1α expression has been reported to be altered in neurodegenerative disorders, leading to mitochondrial defects and increased ROS levels; increasing its levels results in reductions in Alzheimer’s disease pathology and improvements in behavior." (PMID 36568118, 2022). "PPARGC1A and RORA are involved in circadian rhythm; circadian disturbances are one of the earliest symptoms of Alzheimer’s disease." (PMID 31283791, 2019). "While AKT1 and PPARGC1A are not brain-exclusive genes, RNA expression data from the Human Protein Atlas (HPA) confirm their widespread expression across key regions of the human brain, including the hippocampus and cortex—areas central to Alzheimer’s disease pathology." (PMID 40642087, 2025).
Hypertension (47 papers, 2007 to 2025). The presence of chronic increased pressure in the systemic arterial system. "In this work, we observed, for the first time, that that maternal melatonin therapy prevents hypertension associated with increased expression of Sirt1, Sirt4, Prkaa2, Prkab2, Pparg, and Ppargc1a in adult offspring kidneys." (PMID 29641494, 2018). "Human studies have shown associations between a non-synonymous coding variant single nucleotide polymorphism (SNP) in PPARGC1A (G482S; rs8192678) and metabolic outcomes such as adiposity, insulin resistance, type 2 diabetes (T2D), and hypertension." (PMID 35812313, 2022). "However, meta-analysis only indicated modest roles within specific ethnicity and age groups for polymorphisms in the PPARGC1A gene (rs8192678; G482S) with T2D and hypertension." (PMID 35812313, 2022). "The PPARGC1A gene (rs8192678; G482S) was further associated with T2D in a Tunisian population, with waist circumference among Slovenian participants with T2D and with severe hypertension in a Chinese population." (PMID 35812313, 2022). "Moreover, both mitochondrial tRNA 15910 C > T mutation and Gly482Ser polymorphisms in PGC-1α (Pparg coactivator 1 alpha) were associated with essential hypertension." (PMID 36293177, 2022). "The PPARGC1A Gly482Ser polymorphism has also been associated with hypertension in previous studies." (PMID 19077249, 2008). "The Gly482Ser variant of peroxisome proliferator-activated receptor-gamma coactivator 1-alpha (PPARGC1A), a gene related to energy metabolism and mitochondrial biogenesis, was associated with hypertension and CAD." (PMID 39759113, 2025). "Another study demonstrated that maternal melatonin therapy prevented a hypertension programmed high-fructose/high-salt diet by regulating Sirt1, Sirt4, Prkaa2, Prkab2, Pparg, and Ppargc1a." (PMID 31766163, 2019).
prostate carcinoma (47 papers, 2012 to 2025). A carcinoma that arises from epithelial cells of the prostate gland. "Importantly, overexpression of PGC1A (the protein encoded by PPARGC1A) increased FAO flux in PC3 prostate cancer cells, and decreased their proliferation and soft agar clonogenic growth." (PMID 30092766, 2018). "While PPARGC1A amplification appears to be a rare event, important shallow deletions of PPARGC1A have been found in metastasis derived from prostate cancer in human studies." (PMID 29629336, 2018). "Importantly, we show a strong negative correlation between AMPK-regulated cell cycle genes and PPARGC1A expression in human prostate cancer." (PMID 37061917, 2023). "PPARGC1A and ZFHX3 are also reported to be associated with prostate cancer, which could partly explain their ability to predict relapse risk." (PMID 36103249, 2022).
atherosclerosis (46 papers, 2007 to 2025). A disease characterized by the build-up of fatty material and calcium deposition in the arterial wall resulting in partial or complete occlusion of the arterial lumen. "Several processes important for atherosclerosis, such as lipid homeostasis, endothelial function, and inflammation, are potentially modulated by the peroxisome proliferator–activated receptor gamma coactivator-1 alpha (PPARGC1A), encoded by the PPARGC1A gene." (PMID 35812313, 2022). "As a result, the regulation of oxidative stress and lipid metabolism by PPARGC1A may contribute to the onset and progression of atherosclerosis, ultimately leading to cardiovascular disease." (PMID 40423083, 2025).
depression (45 papers, 2009 to 2025). "PPARGC1A possibly binds to RORE sites both on NR1D1 and on ARNTL, and PPARGC1B may act similarly, perhaps providing a partial explanation for effects on both mania and depression, seeming opposites which are both aspects of bipolar disorder." (PMID 19166596, 2009).
myocardial infarction (41 papers, 2011 to 2026). Gross necrosis of the myocardium, as a result of interruption of the blood supply to the area, as in coronary thrombosis. "Other reports using mice with myocardial infarction have also shown GW increases markers of lipid oxidation independent of increased Ppargc1a expression." (PMID 37325367, 2023).
ovarian carcinoma (40 papers, 2016 to 2025). A malignant neoplasm originating from the surface ovarian epithelium. "Patients who carried both BRCA1/2 mutations and PPARGC1A mutations were diagnosed with breast or ovarian cancer at a significantly younger age." (PMID 35625955, 2022). "We then investigated whether PPARGC1A mutations affect age of onset of breast and ovarian cancer in the PCAWG patients." (PMID 35625955, 2022). "A multicenter study on around 3000 single nucleotide polymorphisms (SNPs) and risk for ovarian cancer suggested in 2011 that variants in genes involved in mitobiogenesis, including PPARGC1A, may influence susceptibility to ovarian cancer." (PMID 29361779, 2018). "Knocking out PPARGC1A in breast or ovarian cancer mouse models with mutated BRCA1/2 will also help to investigate the effect of PPARGC1A in increasing cancer risk in the context of BRCA1/2 mutations and to reveal the underlying biological mechanism." (PMID 35625955, 2022). "Importantly, we found that patients with both PPARGC1A and BRCA1/2 mutations were diagnosed with breast or ovarian cancer at a significantly younger age, while the effect of each gene alone was not significant." (PMID 35625955, 2022). "PPARGC1A (PPARG Coactivator 1 Alpha), also known as PGC-1α, is highly expressed in ovarian cancer cells, some researchers showed its high expression in cisplatin-resistant cells, while some others revealed its overexpression could induce cell apoptosis." (PMID 36185201, 2022). "PPARGC1A (PGC-1α) participates essentially in metabolic reprogramming involved in gluconeogenesis, fatty acid metabolism, and mitochondrial biogenesis and facilitates a flexible metabolic profile to benefit tumor cells overexpressing PPARGC1A in human epithelial ovarian cancer cells." (PMID 33921111, 2021).
ischemia (35 papers, 2011 to 2026). A hypoperfusion of the BLOOD through an organ or tissue caused by a PATHOLOGIC CONSTRICTION or obstruction of its BLOOD VESSELS, or an absence of BLOOD CIRCULATION. "In myocardial ischaemia-reperfusion injury, miR-30a-5p exacerbates myocardial damage through the circ_0002612/miR-30a-5p/Ppargc1a/NLRP3 axis, while its inhibition can enhance mitochondrial function by activating SIRT1." (PMID 40504789, 2025).
colon carcinoma (33 papers, 2012 to 2025). "Of the downregulated genes in colon and ovarian cancer, PPARGC1A was reported as a tumour suppressor, and downregulation is associated with poor survival in colon cancer." (PMID 36591282, 2022). "Considering the PPARGC1A and GARBD were consistent in the “tumor vs. normal” and “high-risk and low-risk group,” we further explored the expression of these two genes in colon cancer patients." (PMID 37020539, 2023). "To explore potential colon cancer risk-related genes, we compared the expression of 11 RRGs in normal and tumor tissues and found that PANX2 and GABRD are highly expressed in tumors, while PPARGC1A is less expressed in tumors." (PMID 37020539, 2023). "ALOXE3, PPARGC1A or FABP4 are prognostic biomarkers in colon cancer." (PMID 37055842, 2023). "Thus, it can be inferred that PPARGC1A is a potential therapeutic target for colon cancer." (PMID 38045683, 2023). "By regression analysis, 6 immune-related DEGs (AEN, F2RL1, NR3C2, PPARGC1A, LGALS4, and XDH) were identified as potential prognostic factors, of which AEN, LGALS4, and XDH were used to construct a risk score model, which can effectively predict overall survival (OS) in colon cancer patients." (PMID 36589748, 2022). "Collectively, we screened the six LMGs including CYP19A1, FABP4, LRP2, SLCO1A2, PPARGC1A and ALOXE3, and constructed a signature to predict prognosis and immunotherapeutic response in colon cancer, which was extendedly and externally validated." (PMID 37055842, 2023). "The results showed that the expression levels of ACSL6, CYP19A1, LRP2, OSBPL3 and SLCO1A2 were considerably increased, while those of ACOX1, FABP4, PLAAT5, PPARGC1A and TNFAIP8L3 were decreased in colon cancer." (PMID 38045683, 2023). "Secondly, we studied the expression and pathophysiological significance of CYP19A1 in vitro and in vivo, and further studies are needed on other LMGs including FABP4, LRP2, SLCO1A2, PPARGC1A and ALOXE3 in colon cancer." (PMID 37055842, 2023). "Here we integrated CYP19A1, FABP4, LRP2, SLCO1A2, PPARGC1A and ALOXE3 with clinicopathological information of patients to construct a prognostic nomogram in colon cancer." (PMID 37055842, 2023). "It this study, we found the consistent results by showing that NR5A2, PPARGC1A and LGALS4 were down-regulated in colon cancer cell lines and downregulation of the three genes were related to poor prognosis." (PMID 36440228, 2022). "We found that NR5A2, PPARGC1A and LGALS4 were all down-regulated in colon cancer cell lines, in comparison with normal colon epithelial cell line." (PMID 36440228, 2022). "Only eight genes (UCN, TRIM, RBCK1, TPM2, CD36, NMB, PPARGC1A, and LGALS4) significantly affected the OS in patients with colon cancer (P < 0.05)." (PMID 35572595, 2022). "qRT-PCR was performed from RNA extracted from 43 pairs of colon cancer and adjacent normal tissues to observe the relative expression levels of eight GRGs (P4HA1, STC2, CHPF2, PMM2, PGM2, ENO3, PPARGC1A, and PPP2CB)." (PMID 34422808, 2021). "There was a lower expression of PPARGC1A and a high expression of GARBD in colon cancer patients." (PMID 37020539, 2023). "In our study, based on the colon cancer immune gene datasets, we used WGCNA to identify 21 immune-related hub genes affecting patients’ OS and constructed IRGPI based on 8 independent OS prognostic factors (UCN, TRIM58, RBCK1, TPM2, CD36, NMB, PPARGC1A, and LGALS4)." (PMID 35572595, 2022).
renal fibrosis (32 papers, 2018 to 2025). A final common manifestation of a wide variety of chronic kidney diseases characterized by glomerulosclerosis and tubulointerstitial fibrosis. "Proximal tubule PPARα and PPARGC1a attenuates renal fibrosis and inflammation induced by UUO and other injuries." (PMID 37032786, 2023). "Prior studies have implicated the impact of TGF-β on reduced transcript levels of PPARGC1A in renal fibrosis." (PMID 34609963, 2021). "Hes1 represses ppargc1a during Notch-induced renal fibrosis; however, induced overexpression of ppargc1a can ameliorate this process." (PMID 30475208, 2018).
lung carcinoma (30 papers, 2009 to 2025). "Loss of PGC1α was found to promote lung cancer metastasis through transcriptional circuits regulating EMT-related signaling events in a genetically engineered mouse model with deletion of a single allele of ppargc1a and overexpression of KrasG12V." (PMID 35897813, 2022). "Clinical lung cancer samples revealed a positive correlation between PGC-1α (PPARGC1A) and SIRT1 expression." (PMID 35681729, 2022). "Some published studies have demonstrated that PPARGC1A was upregulated in lung cancer and invasive breast cancer, and facilitated cancer metastasis and invasion." (PMID 33251144, 2020). "Upregulation of PPARGC1A expression can promote the metastasis of lung cancer." (PMID 37903487, 2024). "PPARGC1A is upregulated and facilitates lung cancer metastasis." (PMID 33224957, 2020).
diabetic cardiomyopathy (27 papers, 2008 to 2026). Diabetic cardiomyopathy is a disorder of the heart muscle in people with diabetes. "Previously, we found that uridine could prevent ultrastructural abnormalities and stimulate mitochondrial biogenesis by enhancing Ppargc1a expression in a mouse model of diabetic cardiomyopathy." (PMID 38139129, 2023).
colitis (25 papers, 2019 to 2025). Inflammation of the colon. "Considering the analysis of other genes that could be associated to PPAR-α signaling, mice with experimental colitis, CD and UC patients downregulated Ppargc1a/PPARGC1A expression." (PMID 34434187, 2021). "Epithelium-specific Ppargc1a null mice are more susceptible to DSS-induced colitis compared to wild-type mice, highlighting its participation in colitis pathophysiology." (PMID 36466902, 2022). "During acute colitis, PPARGC1A activation in intestinal CD11b-CD103+DCs promoted the production of retinoic acid, which subsequently acted on CD11b+CD103+DCs to suppress IL-23 secretion." (PMID 33681365, 2021). "Ppargc1a induction is beneficial in maintaining mitochondrial integrity, enhancing intestinal barrier function, and decreasing colitis, which might help to prevent chronic colitis-associated intestinal fibrosis." (PMID 37592304, 2023).